MYCN (MYCN proto-oncogene, bHLH transcription factor)
Diseases named in the same sentence as MYCN in open-access papers (continued):
Sharing a sentence is not in itself a finding about the gene and the disease.
neuroblastoma (continued). "In contrast, MYCN-amplified cell lines exhibited radioresistance under the same conditions, suggesting that targeting Gln metabolism can be beneficial for the treatment of c-MYC-driven but not MYCN-amplified neuroblastoma." (PMID 39199642, 2024). "Despite the extensive study of MYCN-amplified neuroblastomas, there is a significant unmet clinical need in MYCN non-amplified neuroblastomas." (PMID 38553589, 2024). "PKMYT1 inhibition was effective in MYCN-amplified neuroblastomas, but not neuroblastomas without amplification." (PMID 38279263, 2024). "All were diagnosed at <5 years of age and 1 has a MYCN amplified tumor, so these cases are not likely to represent ATRX mutated indolent neuroblastoma, common in older patients." (PMID 38200233, 2024). "For a comprehensive assessment of immune cell infiltration, we used CIBERSORTx deconvolution to quantify various immune populations based on a single cell RNA sequencing (scRNA-seq) dataset in MYCN non-amplified neuroblastoma." (PMID 38553589, 2024). "Similar results were obtained using univariate or multivariate cox regression analysis with age and INSS stages in MYCN non-amplified neuroblastomas." (PMID 38553589, 2024). "We have previously shown that high-level MAX expression in MYCN-amplified primary neuroblastomas confers a poor outcome, while knockdown of MAX in MYCN-amplified cell lines inhibits both cell growth and motility, suggesting that MAX has a critical role in MYCN-mediated oncogenesis." (PMID 38992040, 2024). "These two cell lines respectively represent the MYCN amplified and non-amplified states of neuroblastoma." (PMID 38714539, 2024). "JNJ-64619178 potently reduced cell viability in both MYCN-amplified and non-amplified neuroblastoma cell lines, apart from SK-N-F1, compared to the normal fibroblast cell line." (PMID 38049564, 2024). "In a series of 182 patients with localized, MYCN non-amplified neuroblastoma, in which genotype was determined, only 4% of patients relapsed in metastatic sites." (PMID 38730688, 2024). "Another defining feature of neuroblastoma is a non-linear relationship between the MYCN-amplified clone’s reproductive advantage in a tumour, the tumour’s other mutations, and its gene expression profile." (PMID 39715281, 2024). "In a subsequent study, EPHB2 expression was demonstrated in low-stage neuroblastoma tumors, correlating with MYCN expression in tumors without MYCN amplifications." (PMID 38612645, 2024). "Moreover, expression between MYCN and NOX4 is significantly correlated in MYCN-amplified neuroblastoma samples." (PMID 38493213, 2024). "Owing to the significant inverse correlation shown between MYCN and TNFRSF4 in multiple neuroblastoma datasets, we next aimed to examine whether TNFRSF4 could be a bonafide MYCN target." (PMID 38809883, 2024). "We applied this in our GEMM tumors, a model that develops neuroblastoma because of Cre-conditional activation of the human copy of MYCN in dopamine beta-hydroxylase (Dbh) expressing cells—thus, human MYCN expression should be excluded from non-cancer cells." (PMID 38898465, 2024). "The formulations effectively killed neuroblastoma cells, particularly in MYCN-amplified cases, without damaging the healthy cells." (PMID 38391759, 2024). "Overall, these findings suggest that the relationship between MYCN amplification, TCI, and mesenchymal cell lineage is complex and interwoven and increased understanding of these relationships is vital to understanding the immune component of neuroblastoma." (PMID 39099200, 2024). "First, they compared the inhibitory effect of 4-oxo-isotretinoin with that of isotretinoin on six neuroblastoma cell lines (three with and three without MYCN amplification)." (PMID 38339295, 2024). "To test this, we established patient-derived xenografts using MYCN-amplified T409 and MYCN-nonamplified T423 primary neuroblastoma tumors." (PMID 38493213, 2024).
neuroblastoma (continued). "Using lentiviral transduction to exogenously express the hNET receptor in a luciferase labeled neuroblastoma cell line, we show that the NB1691-LUC/NET model is MIBG avid, MYCN amplified, and radio-resistant, and provides easy tracking of disease with bioluminescence." (PMID 38869684, 2024). "The dependence of MYCN amplified neuroblastoma cells on AF1q expression prompted us to investigate whether AF1q exerts an influence on N-Myc, a key driver in the pathogenesis of neuroblastoma—especially MYCN amplified neuroblastoma." (PMID 38413795, 2024). "Given the observation that TADA2B dependency is strongly enriched in MYCN-amplified neuroblastoma and that TADA2B occupancy is enriched for the MYCN CANNTG motif, we next sought to investigate whether TADA2B colocalizes with MYCN on chromatin." (PMID 38820154, 2024). "Indeed, another study looking to treat neuroblastoma, demonstrated that BAP1 inhibition also destabilised MYCN and thus inhibited MYCN-mediated oncogenic signalling." (PMID 39682746, 2024). "Together, these data suggest that TERT is a MYCN target and the TERT promoter hypomethylated region in neuroblastoma may play a role in the regulation of TERT expression." (PMID 38837897, 2024). "The results showed that loss of JMJD6 greatly reduced the colony numbers in all tested cell lines, demonstrating that JMJD6 is essential to neuroblastoma cells regardless of MYCN amplification." (PMID 38488852, 2024). "Harmaline has been shown to be a moderate enhancer of hClpP activity with moderate cytotoxic activity against both DIPG and neuroblastoma cells, which share the non-amplified MYCN gene involved in tumor onset and progression." (PMID 38276008, 2024). "MYCN amplification correlates with faster tumor progression and advanced disease, which translates to poor event-free survival (EFS) and OS in children and infants with neuroblastoma." (PMID 38891878, 2024). "Treatment of non-MYCN-amplified neuroblastoma cells with TCDD has been found to induce non-apoptotic cell death via an AhR-dependent mechanism." (PMID 38807762, 2024). "We demonstrate that MYCN non-amplified neuroblastomas are heterogeneous and can be classified into 3 subgroups based on their transcriptional signatures." (PMID 38553589, 2024). "The presence of structural changes, regardless of MYCN gene amplification status, influences the clinical behavior of neuroblastoma." (PMID 39049899, 2024). "In our model, ALKF1174L was unable to transform human tNCCs to neuroblastoma in the absence of MYCN." (PMID 38451815, 2024). "In neuroblastoma, G9a and GLP were found to have a positive correlation with MYCN expression, and increased H3K9me2 and H3K27me3 at the CXCL9, CXCL10, and CXCL11 chemokine cluster indicated the potential role of G9a, GLP, and EZH2 in maintaining a ‘cold’ tumor microenvironment." (PMID 39766049, 2024). "We also showed that siRNA knockdown of mitotic genes in established neuroblastoma cell lines was accompanied by reduced cell viability and colony-forming potential, irrespective of cell line MYCN-amplification status." (PMID 37958555, 2023). "In neuroblastoma, Aurora-A depletion mimics the effect of N-Myc deprivation in MYCN-amplified (MNA) but not non-MNA cells." (PMID 36902175, 2023). "Our work establishes that two neuroblastoma cell lines lacking MYCN amplification, murine N2a and human SH-SY5Y, contain cells with gene expression patterns characteristic of both the adrenergic and mesenchymal states." (PMID 38095019, 2023). "We fished out 286 uDEGs in MYCN-amplified compared to non-MYCN-amplified neuroblastoma cell lines and processed them through GOs." (PMID 37835497, 2023).
neuroblastoma (continued). "They found that MYCN-amplified and undifferentiated neuroblastomas had more IDRFs than non-MYCN-amplified or more differentiated tumors." (PMID 36832517, 2023). "This is mainly proven by the guided ectopic expression of MYCN (alone or in combination of LMO1 or ALK) in specific cell lineages of zebrafish models or genetically engineered mouse models (GEMM) which results in the development of neuroblastoma." (PMID 37274289, 2023). "Three different genetically modified zebrafish lines were generated to determine the influence of the TATA/GATA regulatory site on the rate of initiation and penetrance of neuroblastoma: Tg(dβh:MYCN; dβh:EGFP; GATA/GATA), Tg(dβh:MYCN; dβh:EGFP; GATA/TATA), and Tg(dβh:MYCN; dβh:EGFP; TATA/TATA)." (PMID 37183825, 2023). "These discrepancies likely stem from distinct genetic profiles within neuroblastoma; tumors with chromosome 11q deletion or MYCN amplification tend to favor M2 phenotypes, whereas MYCN-nonamplified tumors have a higher prevalence of M1 macrophages." (PMID 38087370, 2023). "Based on that, we speculated that in the context of amplified MYCN, a positive RB1 expression might positively sensitize neuroblastoma cells to CDK4/6 inhibitors." (PMID 36982482, 2023). "An equal number of datasets derived from patient samples from both categories (three MYCN-amplified neuroblastoma and three non-MYCN-amplified neuroblastoma) that are characterized by similar-low enrichment for immune cells (≤10%) were comparatively studied." (PMID 37835497, 2023). "According to the findings 100, TERT activation in high-risk neuroblastoma is not just present in TERTSV+ and MYCN-amplified tumors." (PMID 36860927, 2023). "It has been reported that MYCN can form condensates that may be transcriptionally active, and the IDR and DNA binding domain of MYCN seem to be critical for such condensates in neuroblastoma cells." (PMID 37941901, 2023). "Moreover, as our previous study showed, inhibition of the glycolytic pathway through oncogenic silencing of MYCN reduces glycolytic parameters, but in turn, the FAO pathway becomes dominant for energy reprogramming in the neuroblastoma cell lines." (PMID 37762231, 2023). "In neuroblastoma cells, PA2G4 is a transactivation target for MYCN." (PMID 36980710, 2023). "The expression levels of MYCN and most of the components of NHEJ exhibited a positive correlation, whereas only LIG4 expression had a significant inverse relationship with MYCN expression in the 88 neuroblastoma dataset (Versteeg-88-MAS5.0-u133p2)." (PMID 37240360, 2023). "MYCN-amplification leads to upregulation of hypoxia-inducible factor-1α (HIF-1α), a transcription factor that in concert with MYCN, enhances the expression of glycolytic genes and drives neuroblastoma tumour progression." (PMID 37414143, 2023). "Even among neuroblastomas without MYCN amplification, CIMP was a significant prognostic indicator for patients with poor outcome." (PMID 36831211, 2023). "As with epigenetic drugs used in cancer cells, neuroblastoma cells lacking MYCN also have an enriched H3K4me2 permissive mark combined with a reduction in the repressive marks H3K27me3 and H3K9me3 in the CLU promoter region." (PMID 37685987, 2023). "In vitro, under adherent conditions, CP-d/n-ATF5 dose-dependently inhibited the growth of a panel of neuroblastoma cell lines, both MYCN-amplified and MYCN-non-amplified." (PMID 38014922, 2023). "These binding profiles are mapped in all three MYCN-amplified, but not in non-MYCN-amplified, neuroblastoma cell lines." (PMID 37835497, 2023).
neuroblastoma (continued). "The CCL2/CCR2 axis is pivotal for recruiting monocytes, myeloid cells, and plasmacytoid DCs in MYCN-nonamplified neuroblastoma." (PMID 38087370, 2023). "Molecular mechanisms and gene expression profiles underlying the oncogenic and therapeutic target potential of the 17q oncogene IGF2BP1 and its cross-talk with MYCN were characterized and validated in human neuroblastoma cells, xenografts and PDX as well as novel IGF2BP1/MYCN transgene mouse models." (PMID 37246217, 2023). "For example, NE prostate cancer driven by MYCN is highly dependent on Rb deletion, while high MYCN expression in neuroblastoma does not coincide with Rb deletion." (PMID 37255415, 2023). "A pathological diagnosis of "poorly differentiated neuroblastoma with low mitosis-karyorrhexis index, favorable histology" was made; his tumor cells were hyperdiploid and MYCN was not amplified." (PMID 37238419, 2023). "Given that USP3 is involved in increasing MYCN and snail protein levels, which are key transcriptional factors that regulate neuronal tumors, in this study we explore the post-translational role of USP3 on REST protein during neuroblastoma tumorigenesis." (PMID 37170124, 2023). "MYCN is commonly, but not exclusively, overexpressed in neural-origin cancers, such as neuroblastomas." (PMID 36899853, 2023). "Although BRCA1/2 mutations are not frequent in neuroblastoma, we identified mutational signatures related to HRR deficiency in high-risk non-MYCN-amplified patients." (PMID 37868040, 2023). "The MYCN gene and GD2 are two of the most useful immunotherapy findings for neuroblastoma." (PMID 37239815, 2023). "MiR-186 in NK-Exos could down-regulate aurora A kinase (AURKA) and v-myc avian myelocytomatosis viral oncogene neuroblastoma-derived homolog (MYCN) expression, thereby suppressing cell proliferation and inducing apoptosis in neuroblastoma cells." (PMID 37543612, 2023). "Upregulation of DHX9 protein in high-risk neuroblastomas contingent on MYCN amplification was confirmed by re-analyzing a published mass spectrometry data set35 from 34 (12 with and 22 lacking MYCN amplifications) independent neuroblastoma samples (p = 0.01)." (PMID 37402719, 2023). "When we examined their potencies against neuroblastoma cell lines with and without MYCN amplification, one approved drug stood out: disulfiram (tetraethylthiuram disulfide; sold under the trade name Antabuse)." (PMID 37777587, 2023). "Patients with stage 3 neuroblastoma (NBL) according to International Neuroblastoma Staging System (INSS) without MYCN amplification represent a heterogenous group with respect to disease presentation and prognosis." (PMID 36865795, 2023). "In tumors with amplified MYCN, CLU is strongly downregulated, in part through transcriptional induction of miR-17-92, and it was demonstrated that mice with deregulated CLU are more prone to the formation of neuroblastomas." (PMID 37685987, 2023). "Using mouse and human neuroblastoma cell lines lacking MYCN amplification, we show that the antigen CD49b (also known as ITGA2) distinguishes these subpopulations." (PMID 38095019, 2023). "Two of our hit compounds, #5333 (also called SVI-5333) and #5338 (also called SVI-5338), had a significantly increased therapeutic window compared to WS6 and inhibited the malignant phenotype of neuroblastoma cells in vitro, which partly depended on PA2G4 and MYCN expression." (PMID 36980710, 2023). "Similar predictive specificity and sensitivity of ZNF436 in distinguishing MYCN amplified from MYCN non-amplified neuroblastoma patients was determined in E-MTAB-1781 dataset." (PMID 37904225, 2023).
neuroblastoma (continued). "PMN-MDSC signatures were observed in primary neuroblastoma tumors based on single-cell transcriptomic analysis, with higher proportions of MDSCs detected in MYCN-amplified tumors compared to MYCN-nonamplified tumors." (PMID 38087370, 2023). "In the case of neuroblastoma, it has been observed that tumors where MYCN is overexpressed induce a greater angiogenic response compared to those in which MYCN is not amplified." (PMID 37834193, 2023). "More than 98% neuroblastoma patients with normal 1p were without MYCN amplification, while, 47% neuroblastoma patients with 1p deletion were with amplified MYCN." (PMID 37904225, 2023). "This suggests that BV6 is able to reduce XIAP expression but with less potency than A4 and B3, and may explain why certain neuroblastoma cell lines remain sensitive to BV6 while lines with high XIAP and MYCN expression only respond to A4 and B3." (PMID 37874199, 2023). "MYCN is a major oncogenic driver for neuroblastoma tumorigenesis, yet there are no direct MYCN inhibitors." (PMID 36980710, 2023). "Since MYCN is a transcription factor, we analyzed publicly available MYCN ChIP sequencing data from three neuroblastoma cell lines harboring MYCN amplifications and one cell line without an amplification." (PMID 37402719, 2023). "MYCN-amplified and non-amplified neuroblastomas exhibit varying macrophage infiltration, reflecting distinct immune profiles due to specific genetic alterations." (PMID 38087370, 2023). "These binding profiles are mapped in all three MYCN-amplified, but not in the non-MYCN-amplified, neuroblastoma cell lines." (PMID 37835497, 2023). "Since, age of diagnosis, MYCN amplification and ZNF436 expression were independent prognostic factors in most neuroblastoma cohorts, we speculated the superior prognostic effects in the combinations of ZNF436 with MYCN amplification or age of diagnosis." (PMID 37904225, 2023). "For patients with neuroblastoma without MYCN amplification, it is more likely to exhibit chromosomal alterations and again leads to poor prognostic outcomes." (PMID 37479876, 2023). "In neuroblastoma (n = 148), MYCN non-amplified neuroblastoma cases were enriched in Myeloid Predominant (n = 41, p = 0.007), while neuroblastoma MYCN amplified showed a trend toward Immune Desert (n = 16, p = 0.1)." (PMID 37679810, 2023). "To further corroborate this observation and provide mechanical support for targeting LRP8 in neuroblastoma, we deleted Lrp8 in the murine TH‐MYCN neuroblastoma mouse model and a panel of neuroblastoma cell lines with and without MYCN amplification." (PMID 37435859, 2023). "Our results suggested that E2F1 and E2F3 were prognostic makers of neuroblastoma independent of MYCN amplification and age of diagnosis." (PMID 35764946, 2022). "Overall, the expression patterns observed in neuroblastoma MYCN-amplified samples were in line with the expression of these genes in MYCNARB1PRO, suggesting a broader implication for the observed signatures in MYCN-amplified cancers beyond retinoblastoma." (PMID 36245757, 2022). "Using CRISPR deletion, we generated neuroblastoma cell lines lacking ASCL1 expression, and these grew more slowly than parental cells, indicating that ASCL1 contributes to rapid proliferation of MYCN amplified and non-amplified neuroblastoma cells." (PMID 36263020, 2022). "MYCN amplification is the most important negative prognostic indicator for neuroblastoma patient survival." (PMID 35454859, 2022). "NB risk-classification, established by the International Neuroblastoma Risk Group (INRG), is based on precise prognostic factors (INRG stage, age at diagnosis, histologic category, grade of tumor differentiation, MYCN alterations, 11q aberrations and ploidy) and delineates pretreatment risk-groups." (PMID 36362917, 2022). "Neuroblastoma patients without MYCN gene amplification and even those with unresectable disease and no MYCN amplification have had OS rates of 95–100%." (PMID 36139583, 2022).